IL15 (interleukin 15)
Diseases named in the same sentence as IL15 in open-access papers (continued):
Sharing a sentence is not in itself a finding about the gene and the disease.
lymph node metastasis (3 papers, 2021 to 2026). "The patient collective with lymph node metastasis indicated statistically significant differences in regard to the patient survival outcome in correlation to IL-15 levels." (PMID 32929618, 2021). "Box-plot analysis showed that patients with lymph node metastasis who died during the follow-up period demonstrated considerably increased IL-15 values in contrast to the notable low IL-15 levels in patients with lymph node metastasis who were living at follow-up." (PMID 32929618, 2021). "Moreover, a statistically significant correlation was also proven for the collective with no lymph node metastasis in association to the IL-15 levels and patient survival." (PMID 32929618, 2021).
microcephaly (3 papers, 2019 to 2022). A congenital or acquired developmental disorder in which the circumference of the head is smaller than normal for the person's age and sex. "Unsupervised hierarchical cluster analysis demonstrated that ZIKV-exposed individuals with microcephaly exhibited a tendency of increased levels of pro-inflammatory mediators in CSF, as IL-1β, IL-12p70, IL-15, IL-17A, IFN-γ, and MIP-1α (CCL3) compared to controls." (PMID 33875756, 2021).
neutropenia (3 papers, 2016 to 2023). A decrease in the number of neutrophils found in the blood. "IL-15 injected intravenously in nonhuman primates is known to cause adverse effects such as weight loss and neutropenia." (PMID 37465665, 2023).
ovarian tumor (3 papers, 2021 to 2025). "An oncolytic vaccinia virus expressing an IL-15 superagonist, a fusion protein of IL-15 and IL-15Ralpha, showed potent CD8+ T cell-dependent but NK independent anti-tumour responses in combination with anti-PD1 antibodies in mice challenged with colon or ovarian tumours." (PMID 34888493, 2021).
Parkinson disease (3 papers, 2022 to 2026). A progressive degenerative disorder of the central nervous system characterized by loss of dopamine producing neurons in the substantia nigra and the presence of Lewy bodies in the substantia nigra and locus coeruleus. "LEVODOPA is an effective and well-tolerated drug for the treatment of Parkinson’s disease, which may have a potential association with pSS, this suggests that IL-15 may be a potential target." (PMID 38376769, 2024).
peripheral artery disease (3 papers, 2014 to 2020). "Moreover, IL‐15 is expressed by inflammatory cells localized in the vulnerable atherosclerotic plaques, and serum IL‐15 concentration is significantly higher in patients with CAD or peripheral artery disease than in healthy individuals." (PMID 32406586, 2020). "Moreover, IL‐15 is expressed by inflammatory cells localized to vulnerable atherosclerotic plaques and serum IL‐15 concentration is significantly higher in patients with CADs or peripheral artery disease than in healthy individuals." (PMID 32406586, 2020).
rheumatic diseases (3 papers, 2007 to 2022). "Previous studies had linked IL-15 production with TNF-α stimulation of secreting cells, and TNF-α-targeted therapies have been shown to reduce serum IL-15 levels in patients with rheumatic diseases." (PMID 36009415, 2022). "IL-15 has been evaluated in other rheumatic diseases including SLE, SS, BD and SSc, but its exact role remains obscure." (PMID 35747794, 2022). "Increased serum IL-15 levels have previously been found in sera of patients with various rheumatic diseases and interstitial pneumonia, including seven patients with SSc." (PMID 17784951, 2007). "Clinical trials targeting IL-15 in rheumatic disease are scarce and limited to RA." (PMID 35747794, 2022).
schistosomiasis (3 papers, 2012 to 2023). An infectious disease caused by parasitic trematodes of the genus Schistosoma that colonize human blood vessels and release eggs that can cause granulomatous reactions leading to acute (swimmer's itch or acute schistosomiasis syndrome) or chronic disease. "IL-18 induces IFN-γ together with IL-12 or IL-15 and plays a role similar to IFN-γ, which is supported by our results showing that the expression of IFN-γ and IL-18 in late-staged schistosomiasis patients was significantly lower than that in chronic patients and healthy people." (PMID 37887717, 2023).
Skeletal muscle atrophy (3 papers, 2017 to 2024). The presence of skeletal muscular atrophy (which is also known as amyotrophy). "First, we explored the expression of IL-15, that encodes a myokine that stimulates myofilament protein biosynthesis and is usually suppressed in individuals with muscular atrophy." (PMID 39596480, 2024). "IL-15 has also been identified as a promising therapeutic target for mitigating inflammation-induced skeletal muscle atrophy." (PMID 39026669, 2024). "IL-15 may be an effective therapeutic target for the attenuation of inflammation-mediated skeletal muscle atrophy." (PMID 29021612, 2017).
steatosis (3 papers, 2016 to 2025). Increased lipid within the cytoplasm of cells. "Mice lacking IL-15 or IL-15Rα exhibit reduced intrahepatic CD4+, CD8+, NKT cells, and HSCs and, when subjected to a high-fat diet, display less severe steatosis and lobular inflammation compared to their wild-type counterparts." (PMID 40370443, 2025).
tendinopathy (3 papers, 2012 to 2024). "In our study, the difference of serum levels of IL-6, IL-15, IL-33, and IL-17 are noted before and after serum biomarkers can reflect systemic inflammatory responses, metabolic changes, and tissue remodeling associated with tendinopathy." (PMID 39690426, 2024). "We have previously reported increased levels of IL-15 in early tendinopathy, which shares common cytokine receptor γ-chain (γc), which is a functional component of the IL-21R complex." (PMID 24757284, 2014). "In fact, various inflammatory mediators like TNF-alpha, IL-6, IL-15, IL-18 have been shown to play a role especially in wound healing after injury and in early stages of tendinopathy." (PMID 22480275, 2012). "Thus it may be that downstream activation of the IL-21R complex occurs in tendinopathy via IL-15 costimulation or alterative cytokine interactions." (PMID 24757284, 2014).
toxoplasmosis (3 papers, 2010 to 2016). A parasitic disease contracted by the ingestion or fetal transmission of toxoplasma gondii. "Apart from IL-7 and IL-15, potential role of other γc family members like IL-4 and IL-21 that have been implicated in CD8 memory generation in other infectious disease models, need to be considered in future investigations of memory CD8+ T cell development during toxoplasmosis." (PMID 20520779, 2010). "This suggests that absence of IL-15 or IL-7 alone does not affect CD8+ T cell activation during acute Toxoplasmosis." (PMID 20520779, 2010).
uveal melanoma (3 papers, 2020 to 2023). A melanoma derived from melanocytes of the uveal tract. "Exposure of uveal melanoma cells to IL-15 causes proliferation of tumor cells and decreases the susceptibility of tumor cells to NK cell mediated cytolysis." (PMID 33317028, 2020). "In addition, a study on human uveal melanoma shows that IL-15 administration induces the proliferation of all tested cell lines and decreases their susceptibility to NK cell-mediated cytotoxicity and the response to cisplatin treatment." (PMID 37334356, 2023). "TAMs produce Interleukin-15 (IL-15) and uveal melanoma expresses IL-15 receptors." (PMID 33317028, 2020).
vasculitis (3 papers, 2013 to 2023). "IL-15 was involved in the BD inflammatory process, particularly in vasculitis foci, as an elevated CSF/serum IL-15 ratio characterizes vascular cerebral lesions." (PMID 35956031, 2022).
acute respiratory distress syndrome (2 papers, 2012 to 2019). Progressive and life-threatening pulmonary distress in the absence of an underlying pulmonary condition, usually following major trauma or surgery. "Elevated levels of pro-inflammatory cytokines and chemokines (e.g., TNFα, IFNγ, IL-1, IL-6, IL-8, IL-9, IL-12 IL-15, and IL-17) have been found, up to 10 days after the onset of symptoms, in the plasma of patients with acute respiratory distress syndrome (ARDS) caused by influenza A/H1N1." (PMID 32219005, 2019). "Elevated levels of pro-inflammatory cytokines and chemokines (e.g., TNFα, IFNγ, IL-1, IL-6, IL-8, IL-9, IL-12 IL-15, and IL-17) have been found, up to ten days after the onset of symptoms, in the plasma of patients with acute respiratory distress syndrome (ARDS) caused by influenza A/H1N1." (PMID 23148654, 2012).
airway hyperresponsiveness (2 papers, 2011 to 2022). "IL-15 induction ex vivo and levels in vivo were both related to airway hyperresponsiveness, lower respiratory symptom severity and virus load following experimental RV16 infection in vivo." (PMID 21779162, 2011). "IL-15 levels in BAL fluid were also decreased in asthmatics and inversely related with airway hyperresponsiveness and with virus load during in vivo rhinovirus infection." (PMID 21779162, 2011). "IL-15 levels were significantly lower in asthmatic compared to normal subjects (p<0.05) and were significantly correlated with airway hyperresponsiveness as measured by baseline PC10 histamine (r = 0.47, p = 0.021)." (PMID 21779162, 2011).
allergic asthma (2 papers, 2016 to 2020). A asthma with a basis in a pathological type I hypersensitivity reaction. "IL-15 seems to have a role in the pathophysiology of allergic asthma." (PMID 31996218, 2020). "In this study, we have evaluated the therapeutic effect of an IL-15 / sIL-15Rα complex on pulmonary inflammation and in particular through a mouse model of acute HDM allergic asthma." (PMID 31996218, 2020).
alopecia (2 papers, 2023). Hair loss usually from the scalp. "The level for these biomarkers was not affected by duration or disease activity but it was affected by the types of disease as the concentration of IL-15 and TNF-α were elevated in those patients with totalis type than in other types of alopecia." (PMID 37206670, 2023). "The level for these biomarkers was not affected by duration or disease activity, but it was affected by the type of disease, as the concentrations of IL-15 and TNF-α were higher in patient with Alopecia totalis than in other types of Alopecia." (PMID 37206670, 2023).
amyotrophic lateral sclerosis (2 papers, 2022 to 2025). Amyotrophic lateral sclerosis (ALS) is a neurodegenerative disease characterized by progressive muscular paralysis reflecting degeneration of motor neurons in the primary motor cortex, corticospinal tracts, brainstem and spinal cord. "Moreover, significant induction of G-CSF, IL-2, IL-15, IL-17, MCP-1, MIP-1α, TNF-α, and VEGF levels has been observed in amyotrophic lateral sclerosis (ALS) patients." (PMID 36052093, 2022).
Atrophy (2 papers, 2021 to 2025). Any weakening or degeneration, especially through lack of use. "Intraepithelial lymphocytosis and villous atrophy, both hallmarks of CeD, are thought to be driven by IL-15." (PMID 34257288, 2021).
autoimmune type 1 diabetes (2 papers, 2016 to 2021). Autoimmune disease wherein the body's own immune system attacks and destroys the cells within the pancreas that produce insulin. "We have shown that the pathogenic potential of IL-15 in autoimmune type 1 diabetes (T1D) does not require IL-15Rα." (PMID 34956227, 2021).
benign prostatic hyperplasia (2 papers, 2011 to 2023). A non-cancerous nodular enlargement of the prostate gland. "We evaluated local IL-2, IL-7, IL-15 and IL-21 gene expression in prostate tissues from patients with early stage PCA or benign prostatic hyperplasia (BPH)." (PMID 21943235, 2011).
brain cancer (2 papers, 2018 to 2023). A primary or metastatic malignant neoplasm affecting the brain. "An inverse relationship between pre-diagnostic levels of serum IL-15 and brain cancer risk is plausible biologically." (PMID 30297770, 2018). "In this nested case-control study of first primary brain cancer among active component military personal with serially collected pre-diagnostic serum samples, we found inverse, independent associations between levels of IL-15 and IL-16 and risk of cancer." (PMID 30297770, 2018). "Of 14 cytokines examined, significant inverse associations with brain cancer risk were found for IL-15 and IL-16 when these were modelled either as a quartile trend (P = 0.002 and P = 0.001, respectively) or a log-linear trend (P = 0.001 and P = 0.004, respectively)." (PMID 30297770, 2018). "The inverse association with IL-15 was strongest >7.1 years prior to brain cancer diagnosis (HR = 0.75; 95% CI: 0.61, 0.92) and within 1.8–1.0 years of diagnosis (HR = 0.77, 95% CI: 0.63, 0.95), as well as in individuals ≥35 years old at cancer diagnosis (HR = 0.72; 95% CI: 0.58, 0.90)." (PMID 30297770, 2018). "Our study provides new evidence concerning the possible importance of IL-15 and IL-16 in the aetiology of brain cancer with young and middle age onset." (PMID 30297770, 2018).
bronchiolitis (2 papers, 2021). Inflammation of the bronchioles characterized by swelling of the bronchioles and mucus accumulation. "In another study, IL-15 serum levels correlated with disease severity in children with bronchiolitis." (PMID 33232303, 2021).
candidiasis (2 papers, 2012 to 2023). Infection with the organism Candida. "Dysregulation of IL-15 is emerging as important for the pathogenesis of auto-immune diseases and host immune responses to cancer, and thus IL-15 may exert a protective role against candidiasis by regulating T-cell differentiation, phagocytosis, neutrophil stimulation, or monocyte migration." (PMID 23144764, 2012).
cerebral malaria (2 papers, 2020 to 2024). A sequestration of Plasmodium falciparum in the brain, which can cause coma and/or seizures. "IL-15/IL-15Rα-Fc complexes (IL15C) have also been shown to expand CD8+ T cell, DN T cell and NK cell populations, and to protect mice against cerebral malaria via the induction of IL-10-producing NK cells." (PMID 32753607, 2020).
Chagas disease (2 papers, 2024 to 2025). A parasitic infection caused by Trypanosoma cruzi. "In patients with Chagas disease and preserved EF, the presence of intraventricular conduction disorders appears to be associated with a distinct cytokine profile characterized by elevated IL-10, IL-12p70, IL-2, IL-15, MIP-1α, and IFN-γ." (PMID 41440541, 2025).
cholangitis (2 papers, 2018 to 2020). An acute or chronic inflammatory process affecting the biliary tract. "When we neutralized IL-15, levels of IL-1α were restored and this was associated with attenuated cholangitis." (PMID 29449577, 2018). "On the other hand, we previously reported that obese mice exhibit severe cholangitis related to a combined profile of IL-13/IL-15/IL-17 and indeed IL-15 neutralization attenuated the disease." (PMID 32716024, 2020). "Therapeutic blockade of IL-15 in obese mice with cholangitis resulted in attenuated histological damage, lower numbers of infiltrating neutrophils and CD8+ T cells and reduced levels of proinflammatory cytokines and chemokines including IL-13, IL-17, C-GSF, CCL2, CCL3 and CXCL10." (PMID 29449577, 2018). "In addition we identified IL-15 in our model as a critical factor driving inflammation and tissue damage within the livers of obese mice with cholangitis." (PMID 29449577, 2018). "Immuno-neutralizing antibodies against IL-15 greatly attenuated cholangitis in obese mice." (PMID 29449577, 2018).
chronic obstructive pulmonary disease (2 papers, 2021 to 2023). A chronic and progressive lung disorder characterized by the loss of elasticity of the bronchial tree and the air sacs, destruction of the air sacs wall, thickening of the bronchial wall, and mucous accumulation in the bronchial tree. "Moreover, co-incubation of human peripheral blood NK cells with autologous lung DCs from smokers suffering from chronic obstructive pulmonary disease (COPD) resulted in an IL-15-dependent increased killing of epithelial lungs cells compared to DCs from smokers without COPD." (PMID 34054844, 2021).
cutaneous leishmaniasis (2 papers, 2023 to 2024). Leishmaniasis affecting the skin. "We suggest that in cutaneous leishmaniasis, systemic IL-15 may contribute to the activation of circulating CD8+ T cells and promote CCR5-dependent migration to the site of infection." (PMID 38709823, 2024). "Next, to assess whether IL-15 enhances NKG2D expression on CD8 T cells in cutaneous leishmaniasis, PBMCs from L. braziliensis-infected patients or healthy subjects were cultured in the presence or absence of IL-15 for 18 hours." (PMID 37603573, 2023).
cytomegalovirus infection (2 papers, 2014). A herpesvirus infection caused by Cytomegalovirus. "Previous reports have described that after HCMV infection or priming with IL-15+IL-12+IL-18, NK cells can display memory-like properties and the ability to stably produce high amounts of IFN-γ after rechallenge." (PMID 25329659, 2014). "In addition, during mouse cytomegalovirus infection, NK cells in Nfil3−/− mice expand to numbers similar to those in wild-type mice through an IL-15-dependent mechanism." (PMID 25310240, 2014).
dental caries (2 papers, 2024 to 2025). The decay of a tooth, in which it becomes softened, discolored, and/or porous. "Among the six interleukins measured, only IL-4 and IL-15 showed a significantly higher level in the group of children with dentofacial tissue inflammation compared to the group with uncomplicated dental caries." (PMID 39201367, 2024).
diabetic retinopathy (2 papers, 2020 to 2025). "In analyses of the entire study population and in the German and Korean subgroups, irisin and IL-15 serum concentrations were not significantly different between T2D patients with or without evidence for diabetic retinopathy (data not shown)." (PMID 31506722, 2020).
emphysema (2 papers, 2013 to 2015). "Compared to control smokers, individuals with emphysema had significantly lower log-transformed concentrations of IL-1ra, IL-8 and IL-15." (PMID 23577098, 2013). "IL-15 also favours muscle fibre hypertrophy and antagonises the muscle protein wasting typically seen in patients with cancer or with emphysema." (PMID 23577098, 2013). "Adjusted group comparisons revealed significant reductions in EGF (−0.317, p = 0.01), IL-15 (−0.21, p = 0.01), IL-8 (−0.180, p = 0.02) and IL-1ra (−0.220, p = 0.03) in subjects with emphysema and normal spirometry." (PMID 23577098, 2013). "Regression coefficients showed that, compared to smokers without emphysema, subjects with emphysema had lower levels of EGF (−0.317, p = 0.01), IL-15 (−0.219, p = 0.01), IL-8 (−0.180, p = 0.02), and IL-1ra (−0.220, p = 0.03)." (PMID 23577098, 2013).
enteropathy-associated T-cell lymphoma (2 papers, 2015 to 2023). An uncommon mature T-cell lymphoma of intraepithelial lymphocytes. "IL-15 can have a role in the pathogenesis of the hematological complication of celiac disease (CD), namely enteropathy-associated T-cell lymphoma (EATL)." (PMID 37153603, 2023).
esophageal cancer (2 papers, 2016 to 2022). A primary or metastatic malignant neoplasm involving the esophagus. "The following are being tested: interleukin 15 (IL-15) in patients with advanced cancer, interleukin 12 (IL-12) in patients with esophageal cancer." (PMID 27974927, 2016).
esophageal squamous cell carcinoma (2 papers, 2023 to 2025). Esophageal squamous cell carcinoma (ESCC) is a type of esophageal carcinoma (EC) that can affect any part of the esophagus, but is usually located in the upper or middle third. "PES1 prevents IL-15 expression in esophageal squamous cell carcinoma (ESCC) by interfering with the relationship between ILF3 and IL-15 mRNA, which in turn promotes the breakdown of mRNA." (PMID 40097979, 2025).